EGFR (epidermal growth factor receptor)
Diseases named in the same sentence as EGFR in open-access papers (continued):
Sharing a sentence is not in itself a finding about the gene and the disease.
tumor (continued). "EGFR is a multifunctional receptor involved in proliferation, motility, angiogenesis and survival of tumor cells." (PMID 22825751, 2012). "We found 46% ER/PR-positive tumours, overexpression of EGFR (15%), α-IGF1R (25%), p110α (19%), pAkt (28%), pBad (22%), pmTOR (23%), pMAPK (24%), MUC1 (80%), PTEN loss (20%), and PTEN promoter hypermethylation (20%)." (PMID 22454081, 2012). "The use of drugs that inhibit EGFR-TK and affect NF-κB, a gene whose transcribed products are essential for invasion and metastasis, can induce a more aggressive approach of reducing tumor size and the spread of the disease." (PMID 22187555, 2012). "In the 990141B tumor sample, the presence of a micro-amplification in the EGFR gene results in many mRNA-seq reads that mapped outside of the exon, and that often contain misalignments." (PMID 23284754, 2012). "The average values and standard deviations of the EGFR concentration (EGFR_s) and the phosphorylated TGFα-EGFR complex concentration (phos_TGFaEGFR_s) in the tumor cell cytomembrane were calculated." (PMID 22394427, 2012). "Next, the EGFR ligand binding assay was applied in a proof-of-concept study to profile EGFR in 46 tumor samples derived from breast cancer patients." (PMID 22577549, 2012). "Cetuximab, a chimeric IgG1 EGFR-directed MoAb, has been extensively studied in clinical trials among many tumor types." (PMID 23056941, 2012). "It is established that use of anti-EGFR antibodies such as cetuximab is only cost-effective if used for the treatment of patients with WT K-ras tumours." (PMID 22666589, 2012). "Activation of the EGFR in epithelial cells and their derived tumours including SCC is stimulated by ligand binding that is required to activate its downstream signaling targets that mediate its effects on growth, metabolic activity and cell survival." (PMID 23029387, 2012). "Monoclonal antibodies and small molecule tyrosine kinase inhibitors have been developed to target EGFR in diverse tumor types." (PMID 22359620, 2012). "Based in part on these data, there is biological rationale for the continuation of EGFR TKI treatment upon tumor progression in patients." (PMID 22970367, 2012). "EGFR is a transmembrane receptor tyrosine kinase belonging to the ErbB (also known as HER) family that is activated in many tumours." (PMID 23226727, 2012). "We then compared the LOD of the kit and that of direct sequencing using two EGFR genetically defined standards (ΔE746-A750/+ gDNA Package and L858R/+ gDNA Package), and the 19 EGFR mutant tumours for which an adequate quantity and quality of DNA was available." (PMID 22952784, 2012). "Feeding chronically-inflamed, carcinogen-injected C57BL/6 mice a fish oil containing diet enriched in DHA recapitulated the effects on the EGFR signaling axis observed in cell culture and additionally suppressed tumor formation." (PMID 22761867, 2012). "Linear mixed model results for tumor number and tumor size in the ApcMin/+ and AOM models provide a more detailed assessment of the affect of diet, strain and sex on EGFR inhibition of tumor growth." (PMID 22761823, 2012). "The pharmacokinetic part of the multi-level model will be based on Zalutumumab (2F8), an IgG1 antibody against EGFR that inhibits tumor growth in xenograft models and has shown promising results in phase I/II clinical trials." (PMID 22399130, 2012). "Immunohistological staining of EGFR indicated that high levels of EGFR were present in the cell cultures and tumor xenografts." (PMID 22825751, 2012). "Selective accumulation of EGF-NIR as evident from in vivo competition with cetuximab, was clearly seen after 24 and 48 hours in the tumor and EGFR positive organs such as the liver." (PMID 23144978, 2012).
tumor (continued). "In contrast, we here provide convincing evidence that activation of the proapoptotic BH3-only protein BIM together with EGFR attenuation are key regulators for VPA/HU-induced tumor cell death." (PMID 22289787, 2012). "The tumor-specific EGFR deletion mutant, EGFRvIII, is characterised by ligand-independent constitutive signalling." (PMID 22359620, 2012). "Overexpression of EGFR occurs in 65–70% of CRCs, and as would be suggested by its effects, it is more commonly seen in advanced stage tumours." (PMID 22997602, 2012). "Preclinical studies demonstrated that cetuximab inhibited the growth of EGFR-expressing carcinoma cell lines through cell cycle arrest, antiangiogenesis, antiapoptosis, and inhibition of tumor cell invasion and metastasis." (PMID 22778735, 2012). "Tumour pAkt-IR scores correlated with Gleason score, tumour Ki67-IR (a marker of cell proliferation) and tumour phosphorylated epidermal growth factor receptor (pEGFR)-IR." (PMID 23133535, 2012). "We propose that the GSK3β, β-catenin and MnSOD axis represents a potential target to lower the resistance to oxidative stress of tumor harboring oncogenic EGFR and PI3KCA." (PMID 22662165, 2012). "Specifically, increased expression of EGFR mRNA was found in 45 (37.5 %) tumor tissues, while the increased expression of EGFR protein was found in 41 (34.2 %) tumor tissues." (PMID 22537942, 2012). "Our results showed an increased EGFR mRNA expression in tumors compared to surrounding tissue (p <0.05), with 11% of the cases presenting at least a four-fold difference between tumor and paired adjacent mucosa." (PMID 23207070, 2012). "Immunohistochemistry (IHC) was carried out to detect the protein expression of EGFR in tumor samples." (PMID 23046633, 2012). "On the other hand, it has been reported that a tumor continues to express epidermal growth factor receptor even after developing progressive disease." (PMID 22209766, 2012). "And the small–molecule EGFR inhibitors, gefitinib and erlotinib, has both demonstrated anti-tumor activity in the treatment of advanced NSCLC." (PMID 22916093, 2012). "The overexpression of EGFR is responsible for cell proliferation, tumour cell migration and progression, as well as for the prognosis and the survival." (PMID 22264301, 2012). "We found that in presence of this Met TKi, HGF lost its capacity to recover ErbB2 tumor cells from EGFR inactivation (A+P+H)." (PMID 23028720, 2012). "This variant is expressed on 40% of SCCHN tumors and is responsible for increased proliferation, tumor growth, and chemotherapy resistance to antitumor drugs including the EGFR targeting moAb cetuximab." (PMID 22778735, 2012). "EGFR exons 18–21 were successfully analyzed in 133 tumours by PCR amplification followed by direct sequencing." (PMID 22952784, 2012). "The antitumor effects of CP-358,774 correlated well with inhibition EGFR phosphotyrosine in tumor cells." (PMID 22778735, 2012). "Treatment of TNBC with the new nanobioconjugate results in tumor growth arrest by inhibiting EGFR and its downstream signaling intermediate, phosphorylated Akt." (PMID 22355336, 2012). "Contrasting with other studies, our patients were treated exclusively with transhiatal esophagectomy before providing tumor specimens for EGFR analysis." (PMID 22792097, 2012). "The combined systems biology/ pharmacokinetic model allows us to study two different tumor cell alterations with elevated EGFR levels resulting from (i) an increased receptor synthesis rate; and (ii) a decreased receptor internalization rate." (PMID 22399130, 2012). "To compare the response of normal and tumor cells to anti-EGFR antibodies, we extended our model by integrating a kinetic cellular model representing tumor cells with elevated EGFR levels." (PMID 22399130, 2012).
tumor (continued). "The resulting virus AdΔ24-425S11 produced the bispecific protein 425-s11 during replication in cancer cells, yielding progeny virus with enhanced infectivity and oncolytic properties on EGFR-positive, CAR-deficient tumor cells." (PMID 22312365, 2012). "Accordingly tumor staging also differed between groups: all patients with positive EGFR belonged to stages III or IV, whereas most patients (62%) negative for EGFR had stage I or II lesions." (PMID 22792097, 2012). "Intrinsic resistance (also known as primary resistance) is defined as drug resistance in a tumor that is initially refractory to EGFR TK inhibitor treatment." (PMID 23691449, 2012). "In vivo, BMS-690514 demonstrated antitumor activity in a number of tumor xenograft models in which tumor growth depends on EGFR or HER2 signaling." (PMID 22878519, 2012). "The mRNA expression profile of EGFR was analyzed in 37 matched samples (tumor and adjacent tissue) with a higher median EGFR expression in tumors in comparison with surrounding mucosa (p <0.05)." (PMID 23207070, 2012). "This can be explained by several factors, including higher pTNM scores, poorer tumor differentiation and also older age in the group of patients with positive EGFR." (PMID 22792097, 2012). "Cetuximab is a human-murine immunoglobuin (IgG)G1 mAb that inhibits EGFR by binding to its extracellular domain in both normal and tumour cells." (PMID 22997602, 2012). "Forty-three patients with brain metastases treated with RT, together with EGFR mutation status, demographics, smoking history, performance status, recursive partitioning analysis (RPA) class, tumor characteristics, and treatment modalities, were included." (PMID 23110940, 2012). "The concentration of epidermal growth factor receptor (EGFR) in the tumor cell cytomembranes increases after CTL is added." (PMID 22394427, 2012). "Decreased responsiveness to single-agent VEGFR inhibitors, including motesanib, and epidermal growth factor receptor (EGFR) inhibitors in the Calu-6 model (compared with other tumor xenograft models) have been described previously." (PMID 22992329, 2012). "Automated quantitation of three tumor samples showed levels of EGFR which were below the LOQ as defined by the standard curve in P. furiosus complex proteomic matrix." (PMID 22554165, 2012). "Considering mRNA and protein information, TWIST1 was positive in only one EGFR wild type tumor (sample 133)." (PMID 22272264, 2012). "The results suggest that combination therapy of a chemotherapeutic agent with erlotinib showed stronger antitumor effect compared with chemomonotherapy against erlotinib-resistant tumors in that erlotinib inhibited the phosphorylation of EGFR in the tumor." (PMID 22209766, 2012). "In vitro, the antibodies demonstrated a primarily cytostatic effect against tumor cell lines, while in vivo, treatments with anti-EGFR antibodies were unable to prevent the growth of established tumors in xenograft models." (PMID 23150825, 2012). "EGFR protein expression in tumor samples was quantified using fluorescent immunohistochemistry (IHC) and AQUA® technology." (PMID 22359620, 2012). "The improved response of patients with KRAS wild-type tumours treated with anti-EGFR therapy has been well documented in the literature." (PMID 22240781, 2012). "As we previously demonstrated that EGF-Cy5.5 uptake into the OSCC cells was mediated by EGFR, the fluorescence signal intensity was proportional to EGFR expression of tumor cells." (PMID 23029451, 2012). "EGFR deregulation is common in a variety of tumor subtypes, including NSCLC, where protein overexpression is observed in up to 62%." (PMID 22928112, 2012). "According to some studies, immunohistochemical expression of EGFR in RCC varies from 50% to 90% of tumor cells." (PMID 22475688, 2012).
tumor (continued). "The measurements of EGF-NIR in the tumors normalized to skeletal muscle and compared to the liver, indicated a faster accumulation of the agent in the tumor, compared to the liver, supporting the possibility of a specific EGFR- mediated process." (PMID 23144978, 2012). "In conclusion, this study was the first to demonstrate that ephrinA5S functioned as a tumor suppressor by down-regulating EGFR expression in HCCs." (PMID 22860012, 2012). "In a retrospective analysis of tumor biopsy samples from patients treated in the BR.21 trial, 57% were found to over-express EGFR by IHC." (PMID 22992338, 2012). "Accordingly, in vitro experiments showed combined inhibition of IGF1R and EGFR activity to reduce tumor cell proliferation synergistically." (PMID 22815959, 2012). "Median OS was 28.0 months in patients with WT KRAS tumours who received post-study anti-EGFR therapy versus 20.2 months in those with MT KRAS tumours (HR: 1.68; 95% CI: 1.25–2.26; p = 0.0006)." (PMID 23174912, 2012). "The efficacy of these compounds should apply to tumor cells with a wide spectrum of oncogenic lesions because the Ras/EGFR/PI3K/mTOR pathway is activated in many types of cancer." (PMID 22452803, 2012). "Evaluation of the efficacy of EGFR inhibition on tumor growth showed variable results dependent on diet, model and genetic background." (PMID 22761823, 2012). "Although EGFR mRNA expression showed a relatively strong correlation between the primary tumor and metastases, the correlations of AREG and EREG, which are the ligands of the EGFR family, between primary and metastases were weaker than that." (PMID 22409860, 2012). "Pre-clinical data indicate enhanced anti-tumour activity when combining recombinant human interleukin-21 (rIL-21), a class 1 cytokine, with cetuximab, a monoclonal antibody, targeting the epidermal growth factor receptor." (PMID 22315057, 2012). "In vivo EGFR NIR tumor signal intensity decreased (p<0.05) in As2O3 treated groups versus controls from days 4 to 12, consistent with increasing dosage." (PMID 23029451, 2012). "Poor OS correlated with positive lymph node status (P=0.013), EGFR (P=0.006), p110α (P=0.079), pAkt overexpression (P=0.042), tumour stage (P=0.003), and tumour relapses in the liver (P=0.059) or in CNS (P=0.005)." (PMID 22454081, 2012). "In the present study, the combined treatment of EGFR siRNA and TKIs or antibody achieved increased tumor cell growth suppression (about 30% more at the most) in all the five NSCLC cell lines and increased apoptosis as high as by 100%." (PMID 22436374, 2012). "A new interpretation for this phenomenon would be the upregulation of EGFR in epithelial cells (luminal) as a process of malignant tumor evolution." (PMID 23029631, 2012). "Previous studies have shown that ApcMin/+ tumors display increased EGFR activity, and that treatment with small molecule EGFR inhibitors results in a significant decrease in tumor incidence in these mice." (PMID 22761823, 2012). "The role of the antiepidermal growth factor receptor (EGFR) pathway in tumorogenesis and tumor progression has been well defined." (PMID 23091721, 2012). "It is optimized for the detection of EGFRvIII in FFPE tumor samples because of its sensitivity towards small amplicon sizes and its inability to detect the presence of wild-type EGFR." (PMID 22359620, 2012). "Because EGFR is abnormal in many tumor types and overexpression is critical to disease progression and poor prognosis, inhibition of the receptor with a pharmacologic agent is an important part of cancer therapy." (PMID 25031940, 2012). "e at least EGFR exons 18, 19 and 21, leads not only to new insights in tumor biology but also has great therapeutical impact for the patient." (PMID 23088930, 2012). "The development of a standardized, highly-sensitive, linear, and quantitative assay for EGFR for use in patient tumor tissue carries high potential for identifying those patients most likely to benefit from EGFR-targeted therapies." (PMID 22554165, 2012).
tumor (continued). "Newly formed capillaries delivers a substantial amount of TKI molecules to tumor cells and blocks the EGFR signaling pathway, which lead to an inhibition of tumor growth." (PMID 22935054, 2012). "We are beginning to accumulate evidence that AREG/EREG behave as universal markers for predicting the efficacy of Ctx across most types of EGFR-driven human tumours." (PMID 22491422, 2012). "MoAbs are a very promising class of tumor-targeting agents due to their high specificity for molecular targets such as EGFR and VEGFR." (PMID 22929110, 2012). "Our assay can specifically detect EGFRvIII and can discriminate against wild-type EGFR in FFPE tumor samples." (PMID 22359620, 2012). "Previous reports documented that the anti-tumor effect of certain EGFR-specific mAbs is due to inhibition of ligand binding to EGFR and consequent inhibition of EGFR activation." (PMID 23232108, 2012). "We reveal that curcumin enhances the anti-tumor effects of gefitinib in various resistant NSCLC cancer cell lines by modulating the EGFR protein kinase activity which leads to reduce the cancer cells growth ability and promotes cell apoptosis in vitro." (PMID 21858220, 2011). "The clinical outcomes, including time to tumor recurrence and EGFR TKI treatment outcomes were also studied." (PMID 21858063, 2011). "High amphiregulin expression has been suggested as a positive predictor of sensitivity to anti-EGFR drugs in NSCLC patients, whose tumour had the P-EGFR gene." (PMID 21750552, 2011). "At present, pathological examination is primary method used to assess the ERBB2 and EGFR status of tumor cells." (PMID 21689422, 2011). "The EGF receptor (EGFR) is frequently amplified, over-expressed or mutated in GBM where it plays a vital role in tumor development and maintenance." (PMID 21595984, 2011). "While EGFR is more highly expressed in eRMS tumor tissue ErbB2 expression is more prevalent in aRMS tumor tissue, and found in the majority of RMS tumors in the head and neck." (PMID 21253475, 2011). "The oncogenic Src protein kinase itself is overexpressed in a large number of tumor types and interacts with multiple tyrosine kinase receptors, including EGFR and HER2 to mediate its oncogenic effects of promoting growth and metastasis." (PMID 21689417, 2011). "Mutational analysis of EGFR TK domain (exons from 18 to 21) and immunohistochemistry for EGFR were performed on tumour tissues derived from radical prostatectomy from 100 PC patients." (PMID 21266046, 2011). "Clinical response was reported for EGFR+ tumours: in 9 patients (34.6%) a clinical response was observed (3 (11.5%) Complete Response (CR); 6 (23%) Partial Response (PR))." (PMID 22235224, 2011). "The current research demonstrates that treatment with EGFR-targeted LON/PTX NPs is more effective than combination SOL treatment (decreased tumor volume and decreased tumor weight)." (PMID 21931642, 2011). "Data demonstrating expression of the SGLT1 glucose transporter in tumor cells expressing EGFR suggests that this second family glucose transporters merits examination in addition to the GLUT family." (PMID 21826239, 2011). "Twenty-six (92.9%) out of 28 patients were found to have EGFR+ tumours, whereas the remnant 2 patients (7.1%) had EGFR-tumours." (PMID 22235224, 2011). "Receptor activation of the EGFR leads to the recruitment and phosphorylation of several downstream intracellular substrates, leading in turn to mitogenic signaling and other tumor-promoting cellular activities." (PMID 21197106, 2011). "Inhibition of survival signals and concomitant release of accumulated apoptotic potential jointly contribute to the tumor cell death following the inhibition of addicted oncogene in EGFR addicted cancers." (PMID 22194952, 2011). "In current testing protocols, these tumours would be classified as ‘mutant’, whereas a significant proportion of tumour cells have retained the ability to respond to EGFR inhibitors." (PMID 21712828, 2011).